NGFR (nerve growth factor receptor)
Description:
Low affinity receptor which can bind to NGF, BDNF, NTF3, and NTF4. Forms a heterodimeric receptor with SORCS2 that binds the precursor forms of NGF, BDNF and NTF3 with high affinity, and has much lower affinity for mature NGF and BDNF. Plays an important role in differentiation and survival of specific neuronal populations during development (By similarity). Can mediate cell survival as well as cell death of neural cells. Plays a role in the inactivation of RHOA. Plays a role in the regulation of the translocation of GLUT4 to the cell surface in adipocytes and skeletal muscle cells in response to insulin, probably by regulating RAB31 activity, and thereby contributes to the regulation of insulin-dependent glucose uptake (By similarity). Necessary for the circadian oscillation of the clock genes BMAL1, PER1, PER2 and NR1D1 in the suprachiasmatic nucleus (SCmgetaN) of the brain and in liver and of the genes involved in glucose and lipid metabolism in the liver. Together with BFAR negatively regulates NF-kappa-B and JNK-related signaling pathways.
Synonyms: CD271; TNFRSF16; p75NTR; Gp80-LNGFR; p75(NTR)
Tractability: Small molecule: a structure with a bound ligand is known; a high-quality ligand is known; it belongs to a druggable protein family. Antibody: UniProt places it where antibodies can reach, with high confidence; its Gene Ontology location is reachable by antibodies, with high confidence; UniProt predicts a signal peptide or a membrane-spanning region. PROTAC: a small molecule that binds it is known.
Target class: Membrane receptor
Gene: Protein-coding gene on chromosome 17 (49,495,293 to 49,515,008, forward strand). Ensembl gene ENSG00000064300.
Subcellular location: Cell membrane; Cytoplasm; Perikaryon; Cell projection, growth cone; Cell projection, dendritic spine
Subcellular location (Human Protein Atlas): Nucleoplasm; Plasma membrane
Pathways (Reactome):
Signal Transduction: Axonal growth inhibition (RHOA activation); Axonal growth stimulation; Ceramide signalling; NADE modulates death signalling; NF-kB is activated and signals survival; NFG and proNGF binds to p75NTR; NRAGE signals death through JNK; NRIF signals cell death from the nucleus; Regulated proteolysis of p75NTR; p75NTR negatively regulates cell cycle via SC1; p75NTR recruits signalling complexes
Gene Ontology:
Molecular function: calmodulin binding; coreceptor activity; death receptor activity; protein binding; ubiquitin protein ligase binding; amyloid-beta binding; nerve growth factor binding; neurotrophin binding; signaling receptor activity; small GTPase binding; transmembrane signaling receptor activity
Biological process: cellular response to amyloid-beta; extrinsic apoptotic signaling pathway; negative regulation of blood vessel endothelial cell proliferation involved in sprouting angiogenesis; negative regulation of cell migration; neuron apoptotic process; positive regulation of endothelial cell apoptotic process; positive regulation of miRNA transcription; positive regulation of protein localization to nucleus; Rho protein signal transduction; circadian regulation of gene expression; glucose homeostasis; intracellular glucose homeostasis; intracellular protein transport; circadian rhythm; dorsal aorta development; positive regulation of apoptotic process; presynaptic modulation of chemical synaptic transmission; regulation of cell population proliferation; signal transduction
Cellular component: cytoplasm; plasma membrane; cell surface; cytosol; endosome; extracellular region; membrane; nucleoplasm; perikaryon; cell-cell junction; dendritic spine; growth cone; neuromuscular junction; organelle; postsynaptic density; presynapse
Genetic constraint (gnomAD): Loss-of-function variants: 30 observed, 36.64 expected, observed/expected ratio (o/e) 0.82, 90% interval 0.61 to 1.11. The upper end of that interval is the gene's LOEUF score, 1.11, which puts it in group 4 of 6, group 1 being the genes least tolerant of losing a copy. Missense variants: 529 observed, 574.78 expected, observed/expected ratio (o/e) 0.92, 90% interval 0.86 to 0.99. Synonymous variants: 246 observed, 244.54 expected, observed/expected ratio (o/e) 1.01, 90% interval 0.91 to 1.12.
Homologues: Orthologues: chimpanzee NGFR (100% identical), macaque NGFR (99% identical), dog NGFR (96% identical), guinea pig NGFR (93% identical), mouse Ngfr (92% identical), rat Ngfr (92% identical), pig NGFR (91% identical), rabbit NGFR (80% identical), tropical clawed frog ngfr (54% identical), zebrafish ngfrb (46% identical), zebrafish ngfra (37% identical). Paralogues in human: TNFRSF21 (18% identical), TNFRSF1A (17% identical), TNFRSF11A (16% identical), TNFRSF1B (16% identical), LTBR (15% identical), TNFRSF8 (15% identical), TNFRSF11B (15% identical), RELT (14% identical), CD40 (14% identical), TNFRSF10B (14% identical), TNFRSF25 (13% identical), TNFRSF4 (13% identical), and 9 more.
Diseases named in the same sentence as NGFR in open-access papers:
NGFR is named in the same sentence as 340 diseases in open-access papers, as found by Europe PMC text mining. Sharing a sentence is not in itself a finding about the gene and the disease. The quoted sentences say what the papers report.
melanoma (226 papers, 2005 to 2026). A malignant, usually aggressive tumor composed of atypical, neoplastic melanocytes. "Together, these findings show that NGFR renders melanoma cells less susceptible to NK cell–mediated lysis." (PMID 36638181, 2023). "It has been repeatedly found that subpopulations within melanoma express the neural crest stem cell marker NGFR, which has been linked to tumor initiation, stress responses, phenotype switching, metastasis formation, and therapy resistance." (PMID 36638181, 2023). "Supporting the specific role of NGFR in NK cell suppression, we found that intrinsically NGFRhigh melanoma cells were less susceptible to NK cell killing than NGFRlow melanoma cells." (PMID 36638181, 2023). "CD271 (nerve growth factor receptor; NGFR) is upregulated in a subset of melanoma tumors and is implicated in resistance to both drug treatments and immune responses." (PMID 38067178, 2023). "By blocking SCD, we were able to restore NK cell killing of NGFR-overexpressing melanoma cells in vivo, as reflected by a notable loss of MF438-treated NGFR-overexpressing cells in mice engrafted with human NK cells." (PMID 36638181, 2023). "Male-specific DEGs include MCM7, a DNA replication licensing factor; NKX2-2, an important biomarker for metastatic prostate cancers; and NGFR, the canonical single-pass transmembrane receptor linked to melanoma and squamous cell carcinoma." (PMID 35158998, 2022). "Collectively, these data indicate that TNFα was a potent suppressor of the MITF transcription factor and the associated melanoma antigen Melan A, particularly in the transitory and melanocytic melanomas, whereas NGFR and AXL induction were variable." (PMID 34073253, 2021). "Lastly, given the remarkable resistance phenotype of NGFRhi melanoma cells, it was important to investigate any causal contribution of NGFR." (PMID 32770055, 2020). "This plasticity is seen both in animal models and melanoma patients and is associated with expression of Nerve Growth Factor Receptor (NGFR), a protein originally identified as a putative melanoma stem cell marker." (PMID 32770055, 2020). "Melanoma cell expression of the nerve growth factor receptor CD271 is associated with stem-like properties." (PMID 28852061, 2017). "Unexpectedly, late relapse melanomas exhibited a global loss of melanocytic differentiation markers and a vice versa upregulation of the neural-crest progenitor marker NGFR." (PMID 26530832, 2015). "Nerve growth factor receptor (NGFR/p75NTR/CD271) has been linked to melanoma aggressiveness and therapeutic resistance, but the underlying mechanisms remain unclear." (PMID 42192125, 2026). "In melanoma patients, NGFR was found to be associated with immune rejection and has been shown to predict resistance to anti-PD-1 therapy, while pharmacological inhibition of NGFR can restore tumor sensitivity to T-cell attacks." (PMID 38535990, 2024). "Further evidence supporting a link between NGFR and innate immunity comes from a recent melanoma study wherein tumors deficient in phospho-eIF4E, a translation initiation factor regulating, among others, NGFR, showed increased infiltration of tumor-promoting myeloid-derived suppressor cells." (PMID 36638181, 2023). "Furthermore, NGFR up-regulated sets of cholesterol and fatty acid metabolism genes, inducing changes in the lipid constitution of melanoma cells associated with strongly suppressed NK cell cytotoxicity toward NGFRhigh melanoma cells." (PMID 36638181, 2023). "This might be significant as NGFR expression has been linked to invasive properties of melanoma cells." (PMID 37932277, 2023). "NGFR expression in melanoma cells is associated with increased metastasis and long-term growth." (PMID 36291794, 2022). "In addition, NGFR expression induced by ethanol is linked to immunosuppressive functions and anti-PD-1 immunotherapy resistance in melanoma." (PMID 36291794, 2022).
melanoma (continued). "In addition, high NGFR expression in melanoma cells has been linked to immune exclusion in human melanoma samples." (PMID 35432344, 2022). "NGFR is also associated with tumorigenesis of melanoma, thyroid and breast cancer." (PMID 35280742, 2022). "Lastly, we show that NGFR itself acts as a causal driver influencing melanoma susceptibility to cytotoxic T cells, and that, as a potentially beneficial consequence, this RTK could serve as a therapeutically tractable vulnerability." (PMID 32770055, 2020). "NGFR expression is also associated with downregulation of melanoma antigens, suppression of cytotoxic T cell responses 76 and resistance to adoptive T cell transfer therapy in melanoma patients 85 and mouse models." (PMID 32483452, 2020). "Landsberg and coworkers demonstrated that immunotherapy-resistant melanoma cells xenografted in nude mice models undergo a dedifferentiation process characterized by the concurrent gain of the stemness marker nerve growth factor receptor (NGFR) and loss of TAAs." (PMID 39199632, 2024). "Analysis of melanoma patient samples reveals that high NGFR expression correlates with reduced progression-free survival following immunotherapy." (PMID 42192125, 2026). "Melanoma-derived stem cells release NGFR, which promotes metastasis and lymph node pre-metastatic niche development." (PMID 40758712, 2025). "Inflammatory stress has been found to drive melanoma cell dedifferentiation towards a neural crest lineage, characterized by upregulation of nerve growth factor receptor (NGFR) and downregulation of melanosomal antigens, such as MART-1." (PMID 40001572, 2025). "The first panel highlights melanoma-associated genes, including MITF, AXL, NGFR, TYRP1, and DCT, which are involved in the regulation of melanoma cell identity, dedifferentiation, and invasive potential." (PMID 40909289, 2025). "García-Silva and colleagues demonstrated that melanoma-secreted EVs promote lymphangiogenesis and lymph node metastasis through the nerve growth factor (NGF) receptor (NGFR), which acts on lymphatic endothelial cells." (PMID 40806235, 2025). "Subsequent analyses of this response revealed that nerve growth factor receptor (NGFR/p75NTR) was released as cargo of EVs from metastatic melanoma cells and triggered lymphangiogenic responses, contributing to lymph node metastasis." (PMID 40563616, 2025). "Preexisting cells with high levels of aldehyde dehydrogenase (ALDH) were observed in a gastric cell line, whereas high levels of histone demethylases, tyrosine kinase AXL, and nerve growth factor receptor were observed in melanoma cell lines." (PMID 41304766, 2025). "NGFRhigh/PD-L1high melanoma cells exhibit vasculogenic mimicry in proximity to immune cells, while distinct NGFR spatial patterns are found depending on tumor localization." (PMID 40108693, 2025). "As expected, TNF decreased the gene expression of MITF and its target genes MLANA, DCT and TYR, and, conversely, increased the expression of the stemness factor NGFR in 451Lu melanoma cells." (PMID 39136013, 2024). "It has been shown that melanoma cells resistant to MART-1 T cells express high levels of the stemness marker NGFR." (PMID 39199632, 2024). "Previous reports have linked melanoma tolerance to BRAFi with RTK activity (e.g., AXL, FGFR, NGFR, and EGFR) and ERK reactivation." (PMID 39001489, 2024). "Here, we report that innate immune surveillance by natural killer (NK) cells is bypassed by human melanoma cells expressing the stem cell marker NGFR." (PMID 36638181, 2023). "In sum, we found that NGFR confers innate immune escape to melanoma cells by regulating immune control antagonizing pathways, namely, the suppression of NK cell activating ligands and the activation of fatty acid desaturation." (PMID 36638181, 2023).
melanoma (continued). "In breast cancer and melanoma liver metastases, and in hepatocellular carcinoma, where stromal stains were available, we additionally observed an NGFR stromal gradient across the capsule, resembling that seen in CRLM." (PMID 37596278, 2023). "Other genes and proteins, such as KRAS, NGFR (nerve growth factor receptor), and NRAS (neuroblastoma ras viral oncogene homolog), are also implicated in melanoma BM development." (PMID 37484759, 2023). "Vice versa, it has been shown that melanoma cells with high dissemination capacity express NGFR, which has further been validated as a marker for circulating melanoma cells." (PMID 36638181, 2023). "Intriguingly, human NK cells degranulated less and showed reduced synthesis of TNFα after cocultivation with NGFR-overexpressing melanoma cells compared to control cells." (PMID 36638181, 2023). "Among others, elevated expression of NGFR on melanoma cells has recently emerged as a key driver of invasiveness and metastasis formation." (PMID 36638181, 2023). "Recently, it was demonstrated that EVs from metastatic melanoma cell lines contained nerve growth factor receptor (NGFR), which was delivered to lymphatic endothelial cells and reinforced premetastatic niche formation in lymph nodes of murine model." (PMID 36674479, 2023). "In a previous study we demonstrated that, when temporally overexpressed, NGFR is a potent inducer of melanoma phenotype switching." (PMID 36638181, 2023). "The neural crest stem cell marker NGFR drives melanoma cell metastasis by suppressing NK cell immunosurveillance." (PMID 36638181, 2023). "Using NK cells from randomly selected healthy donors, we found that overexpression of NGFR in melanoma cells led to a reduced NK cell response." (PMID 36638181, 2023). "Specifically, we show that NGFR helps melanoma cells to evade innate immune surveillance by human NK cells, leading to metastasis formation." (PMID 36638181, 2023). "On the contrary, the most recently published study revealed that overexpression of NGFR in melanoma cells resulted in a reduction of NK cell infiltration into xenografts and NK cell-mediated melanoma cell killing." (PMID 37175614, 2023). "Using fluorescent imaging, we observed that NGFR-induced melanoma cells had formed more metastases compared to EV control cells." (PMID 36638181, 2023). "We first overexpressed NGFR in the human melanoma cells in vitro and labeled these with different concentrations of a violet cell tracing dye to allow the discrimination of NGFR-overexpressing (Violetbright) and control (Violetdim) tumor cells in vivo." (PMID 36638181, 2023). "For instance, melanomas primarily composed of the NGFR-expressing NCSC state are the most refractory to not only targeted therapy, but also immunotherapy." (PMID 37563469, 2023). "To address this issue, we first reanalyzed preexisting RNA sequencing (RNA-seq) data from melanoma cells overexpressing NGFR for 24 hours." (PMID 36638181, 2023). "To do so, we performed flow cytometry–based cell surface analysis of well-established NK cell ligands on two human melanoma cell lines (M010817 and A375mel) carrying the Dox-inducible NGFR or EV control construct." (PMID 36638181, 2023). "In order to evaluate the phenotypic diversity of our samples, we mapped the expression profile of key melanoma cell-state regulatory genes such as the NGFR, RXRG, MITF, SOX10, SOX9 and AXL genes." (PMID 36765773, 2023). "Using in vitro and in vivo cytotoxic assays, we show that NGFR protects melanoma cells from NK cell–mediated killing and, furthermore, boosts metastasis formation in a mouse model with adoptively transferred human NK cells." (PMID 36638181, 2023). "In melanoma patients, the dedifferentiated subpopulation with high expression of the NCSC-associated receptor NGFR is associated with immune exclusion and resistance to anti-PD-1 therapy." (PMID 36774337, 2023).